CELSR1 (cadherin EGF LAG seven-pass G-type receptor 1)
Diseases named in the same sentence as CELSR1 in open-access papers (continued):
Sharing a sentence is not in itself a finding about the gene and the disease.
myocardial infarction (2 papers, 2011 to 2023). Gross necrosis of the myocardium, as a result of interruption of the blood supply to the area, as in coronary thrombosis. "Furthermore, a single nucleotide polymorphism (SNP) near CELSR2 on chromosome 1p13 (homologous to CELSR1) is associated with LDL cholesterol and myocardial infarction in a meta-analysis study by Myocardial Infraction Genetics Consortium." (PMID 21698157, 2011).
Stroke (2 papers, 2019 to 2020). Sudden impairment of blood flow to a part of the brain due to occlusion or rupture of an artery to the brain. "Interestingly, CELSR1 has been reported in other GWAS studies as being associated with a variety of traits; these include stroke and a suggestive association with fenofibrate response in diabetics." (PMID 31113495, 2019). "The peak is located within the gene Cadherin EGF LAG Seven-Pass G-Type Receptor 1 (CELSR1), encoding a cadherin super-family cell surface protein identified in GWAS of other phenotypes (e.g., stroke)." (PMID 31113495, 2019).
Cerebral ischemia (1 paper, 2020). Restriction of arterial blood supply to the brain associated with insufficient oxygenation to support the metabolic requirements of the tissue. "CELSR1 has neuroprotective effects in cerebral ischemia/reperfusion injury, and the protective mechanism of CELSR1 seems mainly through the Wnt/PKC pathway." (PMID 32070035, 2020). "In conclusion, this is the first report to explore the neuroprotective effect of CELSR1 on cerebral ischemia by lentiviral knockdown in MCAO rats." (PMID 32070035, 2020). "In this study, we observed for the first time the neuroprotective effect of CELSR1 on cerebral ischemia injury by knocking down the expression of Celsr1 with a lentivirus in MCAO rats." (PMID 32070035, 2020). "To address these questions, we administered lentiviral microinjections to MCAO rats to knock down the expression of Celsr1 to assess the role of CELSR1 in neuroprotection, neurogenesis and angiogenesis in cerebral ischemia in an MCAO model." (PMID 32070035, 2020). "To test whether CELSR1 participates in the process of cerebral ischemia, we investigated the mRNA expression of Celsr1 by quantitative RT-PCR after 2 h of ischemia/22 h of reperfusion." (PMID 32070035, 2020). "Therefore, CELSR1 has a neuroprotective effect on cerebral ischemia injury by reducing cell apoptosis in the peri-infarct cerebral cortex and promoting neurogenesis and angiogenesis, mainly through the Wnt/PKC pathway." (PMID 32070035, 2020). "Thus far, the role of CELSR1 in cerebral ischemia is still unclear." (PMID 32070035, 2020).
COVID-19 (1 paper, 2022). A disease caused by infection with severe acute respiratory syndrome coronavirus 2. "Only one gene, Cadherin EGF LAG Seven-Pass G-Type Receptor 1 (CELSR1), has been found to be shared between COVID-19 and SZ and LOD." (PMID 35185890, 2022).
epilepsy (1 paper, 2019). A brain disorder characterized by episodes of abnormally increased neuronal discharge resulting in transient episodes of sensory or motor neurological dysfunction, or psychic dysfunction. "The nonsense CELSR1 variant in the patient reported here may contribute to epilepsy in the presence of a genetic modifier." (PMID 31190668, 2019).
gastric cancer (1 paper, 2025). A primary or metastatic malignant neoplasm involving the stomach. "CELSR1 is a cadherin superfamily member, and aberrant CELSR1 expression has been observed in various tumor types, including glioma and gastric cancer." (PMID 40446009, 2025).
glomerular disease (1 paper, 2016). "Therefore, future studies may examine the role of Celsr1 in glomerular disease using heterozygous Celsr1Crsh/+ mice or transgenic animals with glomerular-specific deletion of Celsr1." (PMID 27597235, 2016).
hydronephrosis (1 paper, 2016). Collection of urine in the renal pelvis that results in dilatation of the renal pelvis and calyces. "One individual carrying a variant (c.5719_5720 del TG) that generates a truncated CELSR1 protein had unilateral “renal agenesis,” with the opposite renal tract affected by hydronephrosis and hydroureter." (PMID 27597235, 2016). "Another individual, also carrying a protein-truncating mutation of CELSR1 (c.5050_5051 ins GT), had bilateral hydronephrosis, and 3 other patients, all carrying missense CELSR1 variants, were diagnosed as having hydronephrosis, which was bilateral in 2 patients." (PMID 27597235, 2016). "Moreover, according to GenitoUrinary Development Molecular Anatomy Project, Celsr1 is expressed not only in the kidney itself but also in smooth muscle of the mature ureter, and primary defects in myogenic differentiation can lead to functional defects in peristalsis that manifest as hydronephrosis." (PMID 27597235, 2016).
Hypotonia (1 paper, 2025). Hypotonia is an abnormally low muscle tone (the amount of tension or resistance to movement in a muscle). "Hypotonia and seizures were also significantly more frequent in individuals with larger deletions, particularly those affecting TBC1D22A and CELSR1 (χ2 = 18.734; degrees of freedom = 2; p < 0.001)." (PMID 40429797, 2025).
idiopathic scoliosis (1 paper, 2017). A scoliosis with no known cause. "In order to further understand the possible importance of CELSR2 in idiopathic scoliosis, we genotyped common variants within CELSR2 and the related genes CELSR1 and 3, in a large independent case-control cohort." (PMID 29240829, 2017).
mantle cell lymphoma (1 paper, 2019). Mantle cell lymphoma is a rare form of malignant non-Hodgkin lymphoma affecting B lymphocytes in the lymph nodes in a region called the ``mantle zone''. "CELSR1 was part of the apoptosis network, inhibited proliferation of neural progenitor and decreased in non-nodal mantle cell lymphoma." (PMID 31443559, 2019).
polycystic kidney disease (1 paper, 2023). A usually autosomal dominant and less frequently autosomal recessive genetic disorder characterized by the presence of numerous cysts in the kidneys leading to end-stage renal failure. "Additionally, Wnt/PCP is considered a factor involved in polycystic kidney disease development through gene mutations such as CELSR1, CELSR2, CELSR3 (representing cadherin EGF LAG seven-pass G-type receptor 1/2/3), VANGL1 and VANGL2 (representing Vang-like protein 1/2)." (PMID 37762322, 2023).
RASopathy (1 paper, 2023). Developmental syndromes caused by germline mutations (or in rare cases by somatic mosaicism) in genes that alter the Ras subfamily and mitogen-activated protein kinases that control signal transduction. "We describe novel variants in several LA genes, including a likely pathogenic variant in PIEZO1, and VOUS in PIEZO1, ITGA9, CELSR1, EPHB4, and TIE1, as well as novel VOUS in RASopathy genes." (PMID 36959127, 2023).
scoliosis (1 paper, 2017). A congenital or acquired spinal deformity characterized by lateral curvature of the spine. "Future studies, aiming to dissect in further detail the overall importance of the CELSR1-3/associated genes contribution to scoliosis in multiple populations will be undertaken to understand this further." (PMID 29240829, 2017).
Strabismus (1 paper, 2021). A misalignment of the eyes so that the visual axes deviate from bifoveal fixation. "As a result, we found risk variants in four genes (FAT3, KCNH2, CELSR1, and TTYH1) in five families, suggesting their role in development of familial strabismus." (PMID 33435129, 2021). "Despite the small sample study, we were able to identify four genes (FAT3, KCNH2, CELSR1, TTYH1) with causative associations with strabismus." (PMID 33435129, 2021).
vestibular disorder (1 paper, 2021). Pathological processes of the vestibular labyrinth which contains part of the balancing apparatus. "Bearing in mind our results, we believe that clinical research studies should assess vestibular function in patients with neural tube defects and especially with CELSR1 mutations, as vestibular disorders may be diagnosed and appropriate rehabilitation may be prescribed." (PMID 34790090, 2021).
tumor (4 papers, 2017 to 2025). "Only a single tumour contained an edited exonic off-target site (Celsr1)." (PMID 28691711, 2017).
cancer (3 papers, 2019 to 2025). A tumor composed of atypical neoplastic, often pleomorphic cells that invade other tissues. "In carcinomas, the genes related to cell adhesion molecules are MACROD1, CELSR1, and PKP4, with a high-impact mutation detected in PKP4." (PMID 40446009, 2025). "In addition, the non-canonical Wnt/PCP pathway (FAT2, CELSR1, WNT5A), known to suppress early-staged cancers by regulating cell adhesion or migration, was downregulated in group 3." (PMID 30699951, 2019).
kidney disorder (2 papers, 2022 to 2025). A disease involving the kidney. "The genes UPK3A, FBLN1, WNT7B, and CELSR1 have the strongest evidence of association with kidney disorders." (PMID 35741804, 2022). "Using association analysis, candidate gene prioritization based upon a set of known kidney-related genes and estimates of haploinsufficiency, we identified UPK3A, FBLN1, WNT7B, and CELSR1 as priority candidate genes for kidney disorders." (PMID 35741804, 2022). "The results from this study suggest that UPK3A, FBLN1, WNT7B, and CELSR1 are strong candidate genes for kidney disorders in PMS and merit functional studies." (PMID 35741804, 2022).
CELSR1 also shares sentences with these, for which no sentence is quoted: congenital heart defects (2 papers); Sensory hearing loss (2); adenomyosis (1); aortic stenosis (1); brain injury (1); breast tumor (1); chronic obstructive pulmonary disease (1); ciliopathy (1); developmental delay (1); dysplasia (1); Exotropia (1); gastrointestinal disease (1); glioma (1); heart disease (1); Hennekam lymphangiectasia-lymphedema syndrome 2 (1); Hydroureter (1); infection (1); infectious disease (1); intervertebral disc degeneration (1); ischemia (1); ischemic cardiomyopathy (1); kidney malformations (1); lipomyelomeningocele (1); lung carcinoma (1); lymphangiectasia (1); metabolic syndrome (1); myelomeningocele (1); nematode infection (1); neural tube defect (1); neurodegenerative disease (1).
A further 7 diseases each share a sentence with CELSR1 in 1 paper.